Y_RNA (Y RNA )
Gene: Miscellaneous RNA gene on chromosome 9 (65,573,384 to 65,573,495, forward strand). Ensembl gene ENSG00000276723.
Homologues: Orthologues: chimpanzee Y_RNA (96% identical), chimpanzee Y_RNA (95% identical), macaque Y_RNA (89% identical). Paralogues in human: Y_RNA (98% identical), Y_RNA (97% identical), Y_RNA (96% identical), Y_RNA (93% identical), Y_RNA (88% identical), RNY1P5 (85% identical), Y_RNA (85% identical), Y_RNA (84% identical), RNY1 (83% identical), Y_RNA (83% identical), Y_RNA (82% identical), Y_RNA (81% identical), and 99 more.